ZDHHC14 (zDHHC palmitoyltransferase 14)
Description:
Palmitoyltransferase that could catalyze the addition of palmitate onto various protein substrates. May have a palmitoyltransferase activity toward the beta-2 adrenergic receptor/ADRB2 and thereby regulate G protein-coupled receptor signaling. May play a role in cell differentiation and apoptosis.
Synonyms: NEW1CP; FLJ20984
Tractability: Antibody: UniProt predicts a signal peptide or a membrane-spanning region.
Gene: Protein-coding gene on chromosome 6 (157,381,133 to 157,678,157, forward strand). Ensembl gene ENSG00000175048.
Subcellular location: Endoplasmic reticulum membrane; Golgi apparatus, Golgi stack membrane
Subcellular location (Human Protein Atlas): Vesicles
Gene Ontology:
Molecular function: palmitoyltransferase activity; protein-cysteine S-palmitoyltransferase activity
Biological process: peptidyl-L-cysteine S-palmitoylation; protein targeting to membrane
Cellular component: endoplasmic reticulum; endoplasmic reticulum membrane; Golgi cisterna membrane
Genetic constraint (gnomAD): Loss-of-function variants: 15 observed, 44.98 expected, observed/expected ratio (o/e) 0.33, 90% interval 0.22 to 0.51. The upper end of that interval is the gene's LOEUF score, 0.51, which puts it in group 2 of 6, group 1 being the genes least tolerant of losing a copy. Missense variants: 515 observed, 649.26 expected, observed/expected ratio (o/e) 0.79, 90% interval 0.74 to 0.85. Synonymous variants: 293 observed, 272.35 expected, observed/expected ratio (o/e) 1.08, 90% interval 0.98 to 1.18.
Homologues: Orthologues: chimpanzee ZDHHC14 (99% identical), macaque ZDHHC14 (99% identical), dog ZDHHC14 (97% identical), guinea pig ZDHHC14 (97% identical), rabbit ZDHHC14 (96% identical), rat Zdhhc14 (95% identical), mouse Zdhhc14 (95% identical), pig ZDHHC14 (92% identical), tropical clawed frog zdhhc14 (83% identical), zebrafish zdhhc14 (68% identical), Drosophila melanogaster app (48% identical), Caenorhabditis elegans dhhc-2 (30% identical), and 2 more. Paralogues in human: ZDHHC18 (49% identical), ZDHHC9 (43% identical), ZDHHC20 (17% identical), ZDHHC1 (17% identical), ZDHHC2 (16% identical), ZDHHC15 (14% identical), ZDHHC3 (14% identical), ZDHHC12 (14% identical), ZDHHC19 (14% identical), ZDHHC11 (13% identical), ZDHHC4 (13% identical), ZDHHC7 (13% identical), and 5 more.
Diseases named in the same sentence as ZDHHC14 in open-access papers:
ZDHHC14 is named in the same sentence as 26 diseases in open-access papers, as found by Europe PMC text mining. Sharing a sentence is not in itself a finding about the gene and the disease. The quoted sentences say what the papers report.
gastric cancer (3 papers, 2022 to 2023). A primary or metastatic malignant neoplasm involving the stomach. "ZDHHC14 expression is also reduced in several cancer types, including brain tumors; induced in vitro overexpression in gastric cancer cell lines promoted cancer cell migration and cell attachment, in addition to stimulating cell invasion." (PMID 36553552, 2022). "ZDHHC14 overexpression promotes the invasion and migration of scirrhous-type gastric cancer." (PMID 38027033, 2023). "The overexpression of ZDHHC14 in gastric cancer (GC) promoted cancer progression and invasion of cancer cells and might be a promising therapeutic target for the management of GC." (PMID 36286021, 2022).
diabetes (2 papers, 2019 to 2025). "Coding polymorphisms in the consensus Chr 17 area included those linked to cancer (Fndc1, Tiam2, Zdhhc14 Has1), growth and development (Igf2r, Afdn, Tiam2, T2), immunology or diabetes itself via the energetic electron transfer chain (Tiam2, Pde10A) or basal thermal metabolism." (PMID 31661517, 2019).
prostate carcinoma (2 papers, 2023 to 2025). A carcinoma that arises from epithelial cells of the prostate gland. "Consistent with this, we confirmed that ZDHHC14 mRNA levels are downregulated in prostate cancer tissues compared to adjacent normal tissues in two independent GEO datasets." (PMID 39800157, 2025). "ZDHHC14 was identified as the product of a tumor suppressor gene, with decreased ZDHHC14 levels in testicular germ cell tumors and prostate cancer tissue samples and cell lines." (PMID 39800157, 2025). "Moreover, ZDHHC14, as a tumor suppressor, is frequently downregulated in testicular germ cell tumors and prostate cancer, and overexpression of ZDHHC14 resulted in inhibited cell viability and promoted cell apoptosis." (PMID 36018061, 2023).
testicular germ cell tumor (2 papers, 2023 to 2025). A germ cell tumor arising from the testis. "In contrast, P104S mutation (breast cancer) within the third transmembrane segment of zDHHC4 substantially diminished auto-S-palmitoylation, as did L215S mutation (testicular germ cell tumor) in the third transmembrane segment of zDHHC14." (PMID 39800157, 2025).
Cognitive impairment (1 paper, 2021). Abnormal cognition is characterized by deficits in thinking, reasoning, or remembering. "The smallest critical region described so far for 6q25 microdeletion have restricted to a 6q25.3 region including two protein-coding genes, ARID1B and ZDHHC14 which was considered to be responsible for the cognitive impairment and brain anomalies observed in their patients." (PMID 32380822, 2021).
epilepsy (1 paper, 2024). A brain disorder characterized by episodes of abnormally increased neuronal discharge resulting in transient episodes of sensory or motor neurological dysfunction, or psychic dysfunction. "Investigating the catalytic domains and regulatory regions of ZDHHC14, alongside resolving its three-dimensional crystal structure, could facilitate the development of novel therapeutic strategies for epilepsy management." (PMID 39811454, 2024).
Macrocephaly (1 paper, 2022). Occipitofrontal (head) circumference greater than 97th centile compared to appropriate, age matched, sex-matched normal standards. "We retrieved from the DECIPHER database de novo <500 kb CNVs reported on patients with macrocephaly; in four cases, a candidate gene for macrocephaly could be pinpointed: a known microcephaly gene–TRAPPC9, and three genes based on their functional roles–RALGAPB, RBMS3, and ZDHHC14." (PMID 36553552, 2022).
ovarian carcinoma (1 paper, 2021). A malignant neoplasm originating from the surface ovarian epithelium. "In addition, several other potentially interesting targets of YTHDF2 in ovarian cancer have been identified, such as the putative tumor suppressors TRERF1, ZDHHC14, DIS3L, Vps18, NOD1, and SLC9A8." (PMID 33658012, 2021).
retinal disease (1 paper, 2012). "Based on putative function and/or involvement in retinal disease, we selected 16 genes – Bach2, Cdr2, Dusp12, Esrrb, Gpsm2, Haus1, Kdm5b, Lman1, Lrp11, Lrrc2, Ncoa2, Plekha2, Ppargc1b, Trim36, Wisp1 and Zdhhc14." (PMID 22511886, 2012).
tumor (10 papers, 2012 to 2025). "The expression of ZDHHC14 is related to the regulation of integrin α5 and β1 subunit mRNA and protein, with high ZDHHC14 expression primarily promoting tumor cell migration and invasion." (PMID 40681504, 2025). "Overexpression of zDHHC14 decreased viability of 22RV1 cells and suppressed tumor growth in a xenograft model through induction of apoptosis." (PMID 39429488, 2024). "In addition, other genes have been involved in cancer processes, such as interference with innate immune system (SH2D3C), apoptosis (BLCAP), crossing-over regulation during meiosis (RNF212), and tumor suppression (ZDHHC14, MIR138-2, and PHTF1)." (PMID 36535927, 2022). "ZDHHC14 can slow tumor growth and induce apoptosis in human embryonic kidney (HEK 293) cells." (PMID 32863941, 2020).
cancer (9 papers, 2019 to 2025). A tumor composed of atypical neoplastic, often pleomorphic cells that invade other tissues. "In addition to the downregulation of ZDHHC expression, missense and deletion mutations of one or moreZDHHC genes including ZDHHC14 has been associated with a number of varied cancers." (PMID 39800157, 2025). "The PT complex downregulated the gene expression of kinesin-1 light chain 2 (KLC2), mechanosensing PIEZO2, mitochondrial carrier homolog 2 (MTCH2), and ZDHHC14, which are known to enhance the invasion and migration of cancer cells." (PMID 38027033, 2023).
infection (2 papers, 2020 to 2023). The state of being infected such as from the introduction of a foreign agent such as serum, vaccine, antigenic substance or organism. "Robust knockdown of ZDHHC14 protein was achieved one week after infection (>90%), at which point palmitoyl-proteins were isolated from control and Zdhhc14 sh#1-transduced hippocampal neurons using the ABE assay." (PMID 33185190, 2020). "As these symptoms occur in sea bass during infection with NNV, the ZDHHC14 gene is of great interest and deserves to be analyzed further via functional analyses." (PMID 37143017, 2023).
respiratory diseases (1 paper, 2025). "Previously identified smoking-related CpG sites that were also linked to smoky coal combustion – annotated to genes such as AHRR, SNORD93, NWD1, EDC3, STK24, ZDHHC14, HIF3A – converge on key pathways involved in pollutant response, respiratory diseases, and carcinogenesis." (PMID 40236422, 2025).
ZDHHC14 also shares sentences with these, for which no sentence is quoted: coronary artery disease (2 papers); acute myeloid leukemia (1); brain tumors (1); breast carcinoma (1); colorectal cancer (1); depression (1); hepatocellular carcinoma (1); Huntington disease (1); lung carcinoma (1); microcephaly (1); pancreatic cancer (1); Parkinson (1); schizophrenia (1).